IL2 (interleukin 2)
Diseases named in the same sentence as IL2 in open-access papers (continued):
Sharing a sentence is not in itself a finding about the gene and the disease.
pancreatic cancer (continued). "Furthermore, DCs themselves could also infiltrated into the tumors indicating that IL-2 treatment could promote a sustained T cell immunity to pancreatic cancer not only by generating tumor specific T cells but also upregulating DCs infiltration." (PMID 38554155, 2024). "However, the impact of IL2 on DCs in pancreatic cancer is still unclear." (PMID 38554155, 2024). "Furthermore, NK-supernatant differentiated or well-differentiated oral or pancreatic tumor cell lines are not susceptible to IL-2 activated primary NK cell-mediated cytotoxicity; however, they are greatly killed by the CDDP and paclitaxel in in-vitro assays." (PMID 37197660, 2023). "In addition, we have previously reported a cytokine cocktail, consisting of IL-2, IL-15 and IL-21, that leads to the accumulation of central memory tumor infiltrating T-cells (TILs), obtained from patients with glioblastoma as well as pancreatic tumors." (PMID 29854291, 2018). "OAd-TNF-α-IL2 delivers the pro-T-cell cytokines IL-2 and TNF-α in the immunosuppressive TME of pancreatic cancer, and enhances the antitumor efficacy of mesothelin-CAR T-cell therapy." (PMID 40148310, 2025). "Oncolytic adenoviruses (OAds) expressing TNF-α and IL-2 was able to induce CAR-dependent and CAR-independent host immunity and alter the immunosuppressive TME in pancreatic cancer." (PMID 39633491, 2024). "The extradomain B of fibronectin, which is selectively expressed in pancreatic cancer cells, was evaluated as a potential target for the immunocytokine L19-IL2, delivering IL-2 in a specific antibody-mediated manner." (PMID 33466303, 2021). "At 14 days after injection with NK cells, the luciferase signal from the orthotopic pancreatic tumors was significantly reduced in comparison to other groups, showing 7.2- or 6.9-fold higher tumor growth inhibition than PBS or IL-2, respectively (p < 0.01)." (PMID 31324057, 2019). "IL-6 and IL-10 were significantly increased in both the HCC and GBC groups, IL-2, IL-6, IL-10, and TNF-α in the cholangiocellular carcinoma group, and IL-2, IL-6, IL-8, and TNF-α in the pancreatic cancer group." (PMID 29410961, 2017). "DC pulsed with pancreatic cancer cell lysates induced secretion of Th1 cytokine IFN-γ, IL-2 and the Th2 cytokine IL-10." (PMID 25521461, 2014). "In a study conducted on pancreatic cancer models, they developed trivalent CAR T-cells that targets prostate stem cell antigen (PSA), IL-2, and transforming growth factor-B to improve CAR-T cell migration towards the cancer site and overcome the immunosuppressive environment." (PMID 39312080, 2024). "Furthermore, our study found that co-culture with DKK3-overexpressing pancreatic cancer cells upregulated IFN-γ, IL-2, and IL-17, inhibited tIL-4 and IL-10 in activated CD4+ T cells." (PMID 34391478, 2021). "IL-6 and IL-10 were significantly increased in both the HCC and GBC groups, whereas IL-2, IL-6, IL-10, and TNF-α were significantly increased in the cholangiocellular carcinoma group, and IL-2, IL-6, IL-8, and TNF-α were significantly increased in the pancreatic cancer group." (PMID 29410961, 2017). "There are several reports introducing IL-2 producing genes into pancreatic cancer, but there are no reports about IL-2 secreting lymphocytes functioning as immune enhancer cells." (PMID 15329148, 2004). "Thus, this immune competent mouse model replicates the poor in vivo therapeutic efficacy reported in early phase clinical trials of standard anti-mesothelin CAR T cells in pancreatic cancer, making it an ideal model in which to test enhancement of the CAR T cells with synthetic IL-2 circuits." (PMID 36520915, 2022). "Therefore, our report is the first describing CIK cells to have enhanced in vitro cytolytic activity via non-viral interleukin-2 gene transfer against pancreatic cancer cell lines." (PMID 15329148, 2004).
pancreatic cancer (continued). "When the gingival cells from hu-BLT mice were cultured in the presence of IL-2 and the secretion of IFN-γ and IL-8 were determined, there was a significantly lower secretion of IFN-γ from the oral gingiva cells of pancreatic tumor-bearing mice as compared to non-tumor-bearing healthy mice." (PMID 29255459, 2017).
acute myeloid leukemia (61 papers, 1989 to 2026). Acute myeloid leukemia (AML) is a group of neoplasms arising from precursor cells committed to the myeloid cell-line differentiation. "We aimed at determining to what extent NKC haplotypes impact on NK cell repertoire and function, and whether such gene variants impact on outcome of IL-2-based immunotherapy in acute myeloid leukemia (AML)." (PMID 37648262, 2023). "Immunotherapy with histamine dihydrochloride and low-dose interleukin-2 (HDC/IL-2) reduces the risk of relapse in the post-chemotherapy phase of acute myeloid leukemia (AML)." (PMID 31242079, 2020). "HLA-B −21M/T dimorphism is associated with susceptibility to HIV, the killing of HIV-infected cells by NK cells, NK cell anti-leukemic activity, and the overall survival of acute myeloid leukemia patients under IL-2 immunotherapy." (PMID 39857739, 2025). "The NOX2 inhibitor HDC is, in combination with low-dose IL2, approved for remission maintenance in acute myeloid leukemia in Europe." (PMID 38598844, 2024). "The administration of histamine dihydrochloride has received approval in Europe for the treatment of acute myeloid leukemia when combined with the immunotherapeutic agent IL-2, highlighting the potential of histamine in cancer therapy." (PMID 39267843, 2024). "Histamine is an inhibitor of NADPH oxidase (NOX2) and has been approved in Europe in conjunction with interleukin-2 for relapse prevention in patients with acute myeloid leukemia." (PMID 34095230, 2021). "Administering CTV-1-primed NK cells to patients with acute myeloid leukemia has been shown to be more clinically effective than IL-2 activated NK cells." (PMID 31242243, 2019). "HDC is approved in Europe, in conjunction with low-dose IL-2, for relapse prevention in patients with acute myeloid leukemia (AML) who have achieved complete remission (CR) after chemotherapy." (PMID 30315349, 2019). "In this study, 19 acute myeloid leukemia (AML) patients were given haploidentical NK cell infusions together with IL-2 and 5 patients achieved complete remission." (PMID 26089823, 2015). "In a phase I-II clinical trial, IL2 was administered to 10 patients in remission of acute myeloid leukaemia and three with multiple myeloma 1-4 weeks after treatment with ablative chemotherapy or chemotherapy and autologous bone marrow transplantation." (PMID 2803933, 1989). "Indeed, immunotherapy with histamine dihydrochloride and low-dose IL-2 leads to improved clinical outcome in acute myeloid leukemia." (PMID 39759523, 2024). "IL-2, the only cytokine appeared in the 10 largest clusters of citing articles, seems to exert a synergistic effect with antihistamine treatments in patients with acute myeloid leukemia and other cancers." (PMID 35280754, 2022). "Moreover, tumor-derived EVs enriched in TGFβ have been shown to inhibit IL-2-induced T-cell proliferation and to induce regulatory T cell (Treg) phenotype in acute myeloid leukemia (AML), mesothelioma, and colorectal cancer." (PMID 32150875, 2020). "Histamine dihydrochloride administration has been approved in Europe for the treatment of acute myeloid leukaemia, used in combination with the immunotherapeutic agent IL-2, a fact that encourages the study of this biogenic amine as an adjuvant to therapeutic approaches for other cancers." (PMID 31748740, 2020). "Immunomodulatory effects of a HDC-containing regimen on MDSCs were further analyzed in a phase IV trial (Re:Mission Trial, ClinicalTrials.gov; NCT01347996) where patients with acute myeloid leukemia received HDC in conjunction with low-dose IL-2 (HDC/IL-2) for relapse prevention." (PMID 30315349, 2019). "Preclinical studies have demonstrated that the combined application of lirilumab with IL-2-activated HLA-matched NK cells significantly enhances the in vitro lysis of patient-derived acute myeloid leukemia (AML) blasts." (PMID 40463500, 2025).
acute myeloid leukemia (continued). "When comparing newly diagnosed patients with acute myeloid leukemia (AML) and acute lymphoblastic leukemia (ALL), AML showed a significant increase in IL-4, IL-2 and IL-3, and a significant decrease in VEGF and VCAM-1." (PMID 40427092, 2025). "The cell therapy, CYNK-001, was tested in the setting of acute myeloid leukemia (AML) in combination with IL-2 administration." (PMID 38545115, 2024). "In acute myeloid leukemia (AML) patients administered with low-dose IL-2 at 16,400 U/kg subcutaneously three times for 18 months, CD3-CD16-CD56bright and CD3-CD16+CD56+ NK cells increased in the blood, and the expression of NKp30 and NKp46 also increased." (PMID 38698855, 2024). "In preclinical studies, lirilumab enhanced in vitro lysis of patient-derived acute myeloid leukemia (AML) blasts when administered with IL-2 activated, HLA-matched, NK-cells." (PMID 38185735, 2024). "Therefore, we designed a prospective phase I/IIa trial called ‘Infusion of ex vivo-generated allogeneic NK cells in combination with subcutaneous (sc) IL2 in patients with acute myeloid leukemia’ (NCT04347616) to study the safety and efficacy of RNK001 cells with and without IL2 administration." (PMID 37477653, 2023). "In line with this, histamine dihydrochloride administration in combination with IL-2 has been approved in Europe for the treatment of adults with acute myeloid leukemia (AML)." (PMID 35163302, 2022). "In poor prognosis acute myeloid leukemia (AML) patients, NK cell infusions in combination with high dose chemotherapy and IL2 infusion resulted in in vivo expansion of NK cells and complete hematologic remission in 5 out of 19 patients." (PMID 31921174, 2019). "Five out of 19 acute myeloid leukemia (AML) patients attained complete remission; however, high doses of interleukin-2 (IL-2) and high conditioning regimens triggered severe hematological as well as non-hematological toxicities in the patients." (PMID 31546818, 2019). "Histamine dihydrochloride (HDC) plus IL-2 has been proposed as a novel maintenance-immunotherapy in acute myeloid leukemia (AML)." (PMID 27341131, 2016). "In patients with core binding factor acute myeloid leukemia (CBF-AML), positive clinical outcomes were evidenced with IL-2 maintenance therapy." (PMID 41312168, 2025). "After 24 h, the acute myeloid leukemia (AML) cell line HL-60 and healthy peripheral blood lymphocytes stimulated with IL-2 (PBL) were exposed to different concentrations of apicidin or TSA." (PMID 37345145, 2023). "Based on these data patients with acute myeloid leukemia (AML) were treated with HDC and IL-2 (NCT01347996), which resulted in a decrease in monocytic (m)MDSCs." (PMID 37509121, 2023). "Our study supported the oncogenic role of WT1 in myeloid leukemia, and the highlight of this work is the discovery of new WT1 target genes, IL-2, IL-2RB, and IL-2RG, which are likely involved in WT1-mediated leukemogenesis in acute myelogenous leukemia." (PMID 33110919, 2020). "Some studies have reported that interleukin (IL)-2 expansion could recruit and activate key regulators involved in lytic immunological synapse formation of CB-derived NK cells, enabling effective cytotoxicity against killing of acute myeloid leukemia (AML) cells in vitro and in vivo." (PMID 31752805, 2019). "In patients with acute myeloid leukemia (AML), treatment with histamine dihydrochloride (HDC) and low-dose IL-2 (HDC/IL-2) in the post-chemotherapy phase has been shown to reduce the incidence of leukemic relapse." (PMID 29967760, 2018). "In regard of acute myeloid leukemia (AML), we investigated within the NATURIMMUN project NK cells in patients receiving a novel maintenance therapy with histamine plus IL-2." (PMID 28747910, 2017).
acute myeloid leukemia (continued). "Similarly, Acute myeloid leukemia (AML) blasts modified with IL-2/CD80 as a vaccine in vitro can induce peripheral blood mononuclear cells from AML patients to secrete higher levels of IFN-γand show stronger lytic activity against autologous, unmodified blasts." (PMID 39575257, 2024). "Not only are NK cells able to treat solid tumors, but they also play a key role in immunotherapies against hematological cancer like acute myeloid leukemia (AML), by using high doses of these cells or infusing NK cells after chemotherapy along with IL-2 (NCT02763475)." (PMID 34771581, 2021). "In this context it has been recently shown that supernatants conditioned by IL-2-activated NK cells could increase PD-L1 expression on hematopoietic tumor cell lines and primary Multiple Myeloma (MM), Acute Myeloid Leukemia (AML), and Acute Lymphoblastic Leukemia (ALL) cancer cells." (PMID 27294158, 2016). "Kunzmann and coworkers conducted a phase I/II trial of the Zol plus IL-2 regimen for patients with RCC, melanoma, and acute myeloid leukemia (AML)." (PMID 25686210, 2015). "Another group has shown that CM, EM, and effector CD73+CD8+ T cells produce significantly higher IL-2 upon TCR stimulation compared to their negative counterpart in patients with acute myeloid leukemia (AML)." (PMID 35325005, 2022). "In a phase IV trial, eighty-four patients (age 18–79) with acute myeloid leukemia (AML) in first complete remission (CR) received cycles of immunotherapy with histamine dihydrochloride (HDC) and low-dose human recombinant interleukin-2 (IL-2) to prevent relapse in the post-consolidation phase." (PMID 26544512, 2015).
HIV-1 infection (58 papers, 2005 to 2025). The type species of lentivirus and the etiologic agent of acquired immunodeficiency syndrome (AIDS). "HIV-1 infection is associated with dysregulation of cytokine production and can decrease the expression of protective IL-2 via interaction with HIV-1 gp160 and HIV-1 Nef." (PMID 39125034, 2024). "HIV-1 infection was associated with significantly lower production of IL-2, TNF-α and IFN-γ in response to T. gondii from early/asymptomatic stages, when comparing P2 patients to C2 controls." (PMID 37224128, 2023). "In parallel, calcitriol increased cells expressing exclusively CD38 that exhibit lower susceptibility to HIV-1 infection, reduced proliferation and increased production of IL-2 and IFN-γ." (PMID 31550271, 2019). "It has been observed for a long time that HIV-1 infection causes a decrease in IL-2 levels, which is one of the causes of CD4+ T cell depletion, but the mechanism was not clear." (PMID 29426337, 2018). "Both IFN-γ and TNF-α are important mediators of antiviral activity by CD8+ T cells in HIV-1 infection whilst increased production of IL-2 is associated with reduced viral loads in elite controllers." (PMID 27427967, 2016). "IL-2 levels are disturbed during HIV-1 infection, but the underlying mechanism(s) requires further investigation." (PMID 27145859, 2016). "It has been well established for over two decades that HIV-1 infection is branded with loss of T-cell proliferation accompanied with limited IL-2 production." (PMID 23459797, 2013). "Secondly, administration of IL-2 and GM-CSF appeared to rapidly introduce these responses and was associated with clinical recovery in patients with advanced HIV-1 infection." (PMID 16181494, 2005). "The increased secretion of IL-2 by HVEs in response to ellagic acid in the present study suggests that this compound may be able to counteract the suppression of IL-2 caused by HIV-1 infection." (PMID 39125034, 2024). "We have previously shown that IL-2 administration subsequent to immunization was associated with boosted responses to the antigen in question, suggesting a therapeutic role for IL-2 in enhancing proliferative T-cell responses in HIV-1 infection." (PMID 17428345, 2007). "A similar negative regulation has been reported for IL-2 plasma levels, and a reduced frequency of CD8+ T cells producing IL-17 has been associated with persistent immune activation in HIV-1 infection." (PMID 41208973, 2025). "HIV-1 infection is accompanied by dysregulation of cytokine production in vivo and in vitro, with downregulation of interleukin (IL)-2 and interferons and upregulation of proinflammatory cytokines IL-1, IL-4, IL-6, IL-10, and TNFα." (PMID 38280430, 2024). "In a number of studies, HIV-1 infection has been shown to suppress IL-2 expression in Th cells in vitro." (PMID 35164678, 2022). "PHA/IL-2 treatment of TN and TCM induces T cell activation, thus rendering them more susceptible to HIV-1 infection." (PMID 33688006, 2021). "It has also been shown that IL-2+ expressing cells are rapidly lost as a consequence of HIV-1 infection due to high levels of infection." (PMID 31487324, 2019). "Cord blood CD4+ T cells were isolated and made more permissible to HIV-1 infection by in vitro culture with exogenous IL-2 and phytohemagglutinin (PHA) stimulation." (PMID 31772057, 2019). "Since IL-2 is added to our cell culture system to ensure T-cell survival, we are unable to analyze the effects of IL-2 on HIV-1 infection with our system." (PMID 31487324, 2019). "We suspect that a similar effect occurs when HIV-EP2 interacts with IL-2R, as the IL-2/IL-2R regulatory determinant of T cell reactivity is known to be impaired during HIV-1 infection." (PMID 30682089, 2019). "Prevention of spreading HIV-1 infection was assessed in PHA/IL-2-treated PBL (lymphoblasts) after addition of conditioned media from drug-treated MDM." (PMID 29402886, 2018).